CD4 (CD4 molecule)
Diseases named in the same sentence as CD4 in open-access papers (continued):
Sharing a sentence is not in itself a finding about the gene and the disease.
infection (continued). "Primarily, the CD4+ T cells differentiate into the Th1‐type phenotype and produce large amounts of IFNγ in response to infection." (PMID 38770891, 2024). "Utilizing scRNA-seq, we observed an antiviral response via the JAK-STAT pathway to manage the infection, while also contributing to immune response control, such as regulating type II interferon production and CD4-positive, alpha-beta T cell proliferation." (PMID 39584740, 2024). "In both strains, the number of CD4+ cells was lowest and comparable prior to infection, and peaked at day 14, with declining numbers at day 21 and day 28 post-infection." (PMID 38921420, 2024). "Spike can also interact with the cluster of differentiation 4 (CD4) allowing infection of CD4+ T lymphocytes and triggering IL-10 production." (PMID 38549864, 2024). "CD4+ T cells, including helper T cells and regulatory T cells, play vital roles in immune response against infection and disease, which interact and activate other cells in the immune system." (PMID 39134539, 2024). "Mice deprived of CD4 T-lymphocytes at different stages of infection showed disorganization of the granulomatous lesions." (PMID 38392836, 2024). "Our results suggest that onset of infection leads to an increase of proinflammatory macrophages M1 (Fold-Change = 4.4), activated CD4 T cells (FC = 1.8), and activated NK cells (FC = 2.9) (all Padj <0.05, Mann–Whitney tests) in nasopharyngeal samples." (PMID 38236818, 2024). "For instance, in a model of nasal S. pyogenes colonization sensitive to SAg, the removal of CD8+ T cells provided infection protection, whereas in the SAg‐sensitive model of S. aureus bacteremia, removal of CD4+ T cells was protective." (PMID 39286776, 2024). "Another study, NCT03617198, combined a CAR-T cell therapy with ZFN CCR5 modification in a form of dual therapy that ensured that the CD4+ cells are resistant to infection and, at the same time, capable of detecting and clearing HIV-infected cells." (PMID 38474018, 2024). "On the other hand, CD4-positive T lymphocytes are helper T lymphocytes, primarily enhancing phagocyte-mediated anti-infection responses and B lymphocyte-mediated humoral immune responses." (PMID 38974387, 2024). "Like infection, vaccination elicits CD4+ T cells specific to TBEV C, prM/M, and envelope E proteins, with cells specific to two of the four alpha helices of C and domain III of E (EDIII) dominating the response." (PMID 38318179, 2024). "In DTH, an expanding population of antigen-specific CD4 cells release Th1 cytokines that recruit and activate macrophages at the site of infection, resulting in phagocytosis and pathogen killing." (PMID 38920894, 2024). "The proportions of effector CD4 T-, NK, naïve T-, and γδ T-cells decreased after infection, whereas the proportions of effector CD8 T-, Th1, Th2, and Treg cells increased." (PMID 39590301, 2024). "In order to be able to better understand the effect of CAP in particular and of infections in general on the course of CD4, this observation should be examined in further studies with a larger number of cases." (PMID 37423969, 2024). "Recent studies found that reduced numbers of total CD4+ T cells and naive CD4+ T cells at day 28 were significantly correlated with more infections." (PMID 38280072, 2024). "High blood glucose is related to impaired cytotoxicity of CD8+ and NK cells, as well as abnormal cytokine production by CD4+ T cells, in patients with T2D following infection." (PMID 39722811, 2024). "Linear regression analysis adjusted for covariates including duration of HIV infection, duration of infection that was untreated, duration of antiretroviral therapy, nadir CD4 counts, and viral load confirmed these relationships." (PMID 38782925, 2024). "Nef is expressed at high levels early during infection from a multi-spliced transcript and downregulates CD4 by enhancing its internalization and lysosome degradation (92, –, 96)." (PMID 39373535, 2024).
infection (continued). "The major effector mechanisms, especially in live vaccines, are the production of antibodies, induction of strong CD8+ T cell responses, and CD4+ T cell responses against the infection." (PMID 38338687, 2024). "Pregnant women tested in the second month after the onset of infection had a significantly lower response to the IE-1, IE-2, and pp65 than those with remote infection; however, pp65 was the immunodominant target of CD4+ T cells during primary infection." (PMID 39336935, 2024). "Here, an increase in CD8+ T cells was observed immediately following infection, while CD4+ T cells only began to increase significantly in the later stages." (PMID 38535532, 2024). "In contrast to acute phases of infection, at 30 dpi, higher levels of CD4+ and CD8+ T cells in distinct foci were observed in the CNS of surviving 10- and 50-week-old mice." (PMID 39087762, 2024). "In accord, we observed increased Il-10, Cd4, Cd8a, and Foxp3 mRNAs in our RNA-seq data from K-RasLA1 mice on day 7 post-infection." (PMID 39338937, 2024). "The observed differences in cytokine profiles typically generated by distinct CD4+ T-helper cell polarization in response to infection implies T cell responses are integral to shaping outcomes in MRSA bacteremia." (PMID 38779114, 2024). "The low level of CD4 count leads to weakened immune responses and increases their chances of getting infections that the body would normally fight off very easily." (PMID 39664543, 2024). "This case was a forty-three-year-old male with a total CD4 + cell count of 66 cells/mm3 who experienced a chronic form of the infection for at least 5 months after diagnosis." (PMID 38095070, 2024). "For both infection routes, the CD8+/CD4+ T cell ratio in peripheral blood increased progressively over 5 weeks of infection, indicating CD8+ T cell–dominated responses." (PMID 39264727, 2024). "The post-infection antibody titer in the CD4-depleted group was comparable to that in the untreated group, which suggests a role of CD4+ T-cells, in addition to the enhancement of antibody production." (PMID 39066433, 2024). "In the acute infection and recovery stages, we found that the immune function of CD4+ T cells and the cytotoxic function of NK cells mediated by granzyme were inhibited, while CD8+ T cells were mainly cytotoxic cells." (PMID 38898888, 2024). "Mouse splenic and liver CD4+ DEGs were obtained by comparing the naïve and infected states (day 56 post-infection)." (PMID 38881737, 2024). "Within the study cohort, across each of the examined years, MSM consistently presented with the least advanced stage of infection, as evidenced by a notably higher median CD4+ T cell count (465/μL), in contrast to IDUs (327/μL) and HTXs (250/μL)." (PMID 39339921, 2024). "A low CD4 T cell count and a low CD4:CD8 ratio were significantly associated with concomitant infection with helminths and the Mtb complex (Mtb+/Helm+) compared to the other groups (p < 0.05)." (PMID 39062045, 2024). "Here, HTLV-1 was detected in both CD8+ and CD4+ T cells one-week post-infection (wpi); at five wpi, the predominant cell type that was observed was CD4+ T cells, indicating that preferential tropism arises in the chronic phase of the disease." (PMID 39459949, 2024). "The study provides additional evidence that a low CD4:CD8 ratio carries an additional risk for ADM and infection-related malignancies." (PMID 38092042, 2024). "FN1 also binds to HIV-1 gp120, which has been shown to enhance complement interaction and infection of primary CD4 + T-cells." (PMID 39632834, 2024). "Together these data show that IL-6 (but not CD4 cells) contributes to the initial awakening and expansion of dormant DCC, but that later during the infection following the recruitment of T cells, CD4 cells are required for the maintenance of the awakened DCC." (PMID 38645169, 2024).
infection (continued). "In individuals with T2DM, CD4+ T cells are less effective in producing IFN-γ, compromising the immune system’s ability to control the infection and increasing the risk of chronic or reactivated TB." (PMID 39770852, 2024). "Through T cell depletion using antibodies before infection, we discovered that CD4+ and CD8+ T cells have distinct roles in the upper and lower respiratory tract." (PMID 39178263, 2024). "This 27–32 KDa protein is expressed from early on in the infection process and is key in many aspects of viral infection and CD4+ T-cell suppression." (PMID 39086659, 2024). "Lastly, during humoral responses, B cells are recruited to the infection site and are activated by CD4+ T cells to produce antibodies, IgA and IgG." (PMID 39698320, 2024). "We observed a significant increase in activated SARS-CoV-2-specific CD4+ T cells at pre-immune and 2 to 8 weeks post-infection times for R (p<0.05)." (PMID 38812507, 2024). "Whilst previous studies in SARS infection found that central memory T cell responses persist for up to 4 years post infection, a recent study of 188 patients has shown that memory CD4 and CD8 T cell numbers decline with a half-life of 3–5 months." (PMID 38212801, 2024). "The shift in CD4+ cells in the trachea from CD4+TCRαβ2+ to CD4+TCRαβ1+ during the infection suggests a change in T-cell immunity in the trachea after infection." (PMID 38474071, 2024). "As the infection was controlled, the CD4+ T cell numbers in 70-DPI survivors dramatically decreased, approaching levels comparable to those observed in naïve or vaccinated mice at 0 DPI." (PMID 38712080, 2024). "We show that TCR-mediated activation of peripheral Vδ1 T cells induced de novo upregulation of CD4 providing a plausible mechanism for increased permissibility to infection." (PMID 39149467, 2024). "At 7 dpi, an increase in the mRNA expression of IFN-γ was observed in birds infected with IBDV when compared with mock-inoculated birds, implying that CD4 cells at this time point mounted an effector response aimed at clearing the infection." (PMID 37744374, 2023). "Inhibition of IL‐27 during acute infection allowed maintenance of higher levels of memory CD4+ T cells and antibody, contributing to better protection upon reinfection, which depended on persistence of the infection." (PMID 37855243, 2023). "The activation of CD4+ T cells can effectively target the infection of Salmonella, therefore, if Salmonella wants to establish a systemic infection, it must interfere with the normal biological function of DCs." (PMID 37081875, 2023). "This possibility is consistent with studies reporting the preferential infection of ⍺4β7high CD4+ T cells in vitro and in vivo." (PMID 38064524, 2023). "We found that soluble TNF is involved in the migration of CD4 + cells during infection and the synthesis of chemokines." (PMID 38036985, 2023). "During severe infection, general lymphopenia is associated with an increased number of circulating plasmablasts, Th1-like CD8 and CD4 cells, megakaryocytes, and erythroid cells." (PMID 36445762, 2023). "Unfortunately, infection of CD4+ T-cells by HIV results in their destruction (via apoptosis, pyroptosis, and/or cytotoxic T-cells), which further augments the absence of a robust immunological response against HIV infection." (PMID 38005875, 2023). "Nevertheless, our study suggests that DNA methyltransferase inhibition induces CD4+ T cell plasticity in the lung cells of neonates to activate transcriptional programming resembling the mature response to infection." (PMID 36922640, 2023). "The early infection group had more patients with CD4+ T-cell counts < 300/μL (P = 0.005), as well as higher interleukin (IL)-6 (P < 0.001) and IL-8 (P = 0.013) levels." (PMID 37360336, 2023). "At 10 day postexposure, CD4+ T cell levels in the MGT from infected animals were similar to those found prior to infection." (PMID 37306625, 2023).
infection (continued). "Notethat for a RP infection course, both equilibria are character-ized by a depleted CD4+ T cell population, with macrophagesbeing the dominant source of viruses." (PMID 38213700, 2023). "Protection was abolished following CD4+ T cell depletion during either vaccination or infection but was retained if CD4+ T cells were only partially depleted." (PMID 36732332, 2023). "Early after infection, we also observed the presence of polyfunctional memory CD4+ T cells capable of producing, simultaneously, IL-2 and IFN-γ." (PMID 38006037, 2023). "Five weeks later, after recovery from infection, mice were treated with tamoxifen and further 3 weeks later, CD4+ T cells from spleen, mLN and SI were analyzed." (PMID 37469513, 2023). "During acute infection, viremia rapidly increases and CD4+ T cell numbers decline, both as a direct result of infection and cytotoxic T cell killing and as an indirect result of immune hyperactivation and bystander killing." (PMID 37632019, 2023). "In both of our models, we saw little change in TCR usage within CD4+ populations prior to late infection when CD4+ T cell lymphomagenesis was likely to be occurring." (PMID 36992316, 2023). "Additional experiments showed that infection of MDMs was more effective when co-cultured with primary autologous CD4+ T cells infected for 2 d compared with infected counterparts for 9 d." (PMID 36988579, 2023). "We reported that RHV clearance in lab mice is T cell-dependent since selective depletion of CD4 T cells before infection resulted in chronic RHV infection, and transient depletion of CD8 T cells delayed RHV clearance." (PMID 37812637, 2023). "Flow cytometry and t-distributed stochastic neighbor embedding clustering analyses identified Rora-expressing CD45+ cells, including a population of Rora-expressing ILC2 and CD4+ T cells in lungs of mice 7 d after primary infection." (PMID 37387671, 2023). "We first evaluated the role of T-cells in control of MA-CCHFV infection by investigating the consequence of depleting either CD4+, CD8+ or both CD4+ and CD8+ T-cells on clinical disease progression." (PMID 37866114, 2023). "Body fluids such as semen, vaginal fluids and blood of infected persons contain free-floating viruses and virus-infected CD4+-positive cells that facilitate the transmission of infection to the next cell or host." (PMID 37408185, 2023). "The proportions of central memory, effector memory and GLUT3+ effector memory CD4+ T cells were also significantly different at the late time points depending upon vaccination or infection as the initial antigen exposure route." (PMID 37790414, 2023). "This study will provide insight into the cytokine status at the early stage of disease and has the potential to identify novel biomarkers that can predict virus replication and peripheral CD4+ T cell levels during early infection." (PMID 36851142, 2023). "CD4+ T cell responses are the final output in a long series of steps following infection and are influenced by antigen-dependent and independent factors." (PMID 37058141, 2023). "In this study, we investigated the effect of GPI-scFv X5 expression on CD4+ cell lines and primary human CD4+ T cells with regards to their ability to block trans-infection of HIV-1 captured by iDCs or mDCs." (PMID 37781368, 2023). "According to the 2020 data from the ECDC, 51% of those with a new infection were diagnosed with HIV while having a CD4+ cell count of less than 350 cells/mm3." (PMID 36892474, 2023). "This virus mainly infects CD4+ T cells, with a particularly high infection rate for CCR4+CD4+ T cells." (PMID 37378292, 2023). "Naïve CD4+ T cells, developed after primary infection, differentiate into many types of memory T cells that preserve information about previous infection." (PMID 38004749, 2023). "Two macaques (RM12 and RM13) had a dramatic reduction in CD4+ T cells and died on day 22 and day 44 after infection, respectively (50% survival rate)." (PMID 37695104, 2023).
infection (continued). "In particular, CD4+ lymphocytes are crucial for the resolution of infection; mice depleted with anti-CD4+ antibody have markedly decreased immunity." (PMID 37325809, 2023). "Infection with measles virus abrogates the DC’s ability to stimulate the proliferation of naïve allogeneic CD4+ T cells." (PMID 38077365, 2023). "During acute HCV infection, patients with a self-limiting infection and those who progress to chronicity initially have a comparable functional CD4+ T cell response targeting multiple viral epitopes." (PMID 36992265, 2023). "Various T cell subsets have been shown to play essential roles during S. aureus skin and soft tissue infections, where CD4+ and ɣδ T cells are critical for infection containment." (PMID 37179295, 2023). "After infection, pre-existing CD4 T cells enhance the Ab response to the same protein and accelerate GC formation without affecting antigen-specific B cell frequency." (PMID 37711622, 2023). "How CD4 + T cells from Uganda HIV controllers avoid infection and depletion upon encountering the virus remains incompletely understood." (PMID 37231494, 2023). "More specifically, these human cell infection-tropic viruses include the cellular primary receptors CD4 (T-helper-cell marker antigen) utilized by HIV-1 and angiotensin-converting enzyme-2 (ACE2) utilized by SARS-CoV-2." (PMID 38155835, 2023). "Once infection is cleared, antigen‐specific effector T cell (CD4+ and CD8+ T) populations decline and a small cellular subset is maintained as antigen‐specific effector and long-lived memory T cells (CD4+ and CD8+ T cells)." (PMID 37153606, 2023). "Our analysis of available PBMC specimens from 24 breakthrough cases (8 OA and 16 HCW) indicated that infection boosted the percentage of both spike-specific CD4+ and CD8+ T-cells (P≤0.008 for all paired longitudinal comparisons)." (PMID 38035132, 2023). "During an i.c. infection of Cn, depletion of CD4+ T cells or neutralization of IFN-γ was shown to exacerbate murine CNS infection, suggesting a critical role for cell-mediated immunity mechanisms in acquired protection in the CNS." (PMID 36786559, 2023). "The combined upregulation of CD25 and CD134 allows the identification of antigen-specific CD4+ T cells in TB and various other infections." (PMID 37809012, 2023). "On day 14, BPD-associated CpGs were highly enriched in neutrophil activation, infection, and CD4 + T cell quantity, and BPD-DEGs were involved in DNA damage, cellular senescence, T cell homeostasis, and hyper-cytokinesis." (PMID 37507442, 2023). "CD4+ T cells were strongly increased in both lines by day 21 with infection (p < 0.001), from 16–25% of the splenic lymphocyte population in controls to 44–74% in infected birds." (PMID 36992316, 2023). "In Fiebig I, prior to immune activation in response to infection, HIV interacts with susceptible target cells in LT that are nearly exclusively resting CD4+ T cells." (PMID 37733443, 2023). "The other differentially expressed surface markers in HIV+ cells reflect the known preferential infection of activated CD4+ T cells." (PMID 36536105, 2023). "A common signature among these infections is a strong dependence on CD4+ T cell responses for host immunity, although how such responses can be effectively induced in a vaccine setting remains a key challenge." (PMID 37733817, 2023). "We transferred either Nur77-GFPLO or Nur77-GFPHI CD4 T cell populations into infection time point matched, congenically distinct wildtype mice (CD45.1) at four weeks post-infection." (PMID 38110410, 2023). "Research has demonstrated that Gal-3 can bind to HIV-1 gp120 and CD4 proteins, enhancing viral entry and infection." (PMID 37298569, 2023). "The systemic control and clearance of primary infection with attenuated S. Typhimurium requires Th1-polarised CD4+ T cells, while a Th17 population contributes to controlling extracellular bacteria from breaching the gastrointestinal barrier." (PMID 37733817, 2023).